CCND1 (cyclin D1)
Diseases named in the same sentence as CCND1 in open-access papers (continued):
Sharing a sentence is not in itself a finding about the gene and the disease.
breast cancer (continued). "Dietary behaviours and body constitution may be associated with specific types of breast cancer defined by conventional pathology parameters and cyclin D1 and cyclin E expression." (PMID 17254341, 2007). "Besides a potential role for cyclin D1 in ERα response, cyclin D1 has also been linked to prognostic information in breast cancer." (PMID 15138475, 2004). "Cyclin D1 aberrations have been strongly linked to human breast cancer." (PMID 11870541, 2002). "Collectively, increased expression of DILA1, Cyclin D1, and p-Rb(Ser780) protein are associated with tamoxifen resistance and poor prognosis of ER-positive breast cancer patients who received adjuvant tamoxifen treatment, consistent with the findings in tamoxifen-resistant breast cancer cell lines." (PMID 33139730, 2020). "Similarly, CCND1 amplification was associated with poorer survival in luminal A—with a notable deviation between survival curves after 5 years, endocrine-treated and untreated breast cancer patients (P = 0.019, 0.007 and 0.014, respectively)." (PMID 30819233, 2019). "Furthermore, Julietet al. found that functional risk SNPs (rs554219 and rs78540526) at the 11q13 locus for breast cancer could regulate CCND1 expression through long-range regulation, which located approximately 125kb downstream." (PMID 27603140, 2016). "This could partly explain why cyclin D1 overexpression is associated with 50% of breast cancers." (PMID 25364741, 2014). "Moreover, in breast cancer tissues activation of the ERα-coupled Bmi1 pathway generally correlated with high levels of cyclin D1, while loss of its activity resulted in aberrant expression of p16INK4a and a high Ki-67 index, which implied a more aggressive phenotype of breast cancer." (PMID 24559156, 2014). "Hence, our results suggest that loss of YAP1 may confer aggressiveness in ER+ breast cancers independently of the established oncogenic CCND1 amplification." (PMID 24559095, 2014). "Together, these results indicate that TGFβ-induced cyclin D1 expression correlates with TGFβ-induced p21 gene expression and cell migration, thus, suggesting that cyclin D1 may be associated with p21 and participate in TGFβ tumor-promoting functions in breast cancer cells." (PMID 23786849, 2013). "Moreover, the mechanism underlying the elevated expression of Cyclin D1 in breast carcinomas remains unknown." (PMID 23327593, 2013). "This indicates that stiffness alone influences CCND1 expression in luminal breast cancer cells, potentially via YAP-independent mechanisms." (PMID 41536990, 2026). "In summary, the E2/PAK4/Cyclin D1 signaling axis plays a pivotal role in regulating proliferation, cancer stemness, and bone-specific metastatic behavior in ER+ breast cancer." (PMID 41596432, 2026). "For example, overexpression of cyclin D1 mRNA is strongly correlated with poor prognosis in estrogen receptor-positive (ER+) breast cancer." (PMID 41424847, 2026). "Data analysis from TCGA (accessed through the UNLCAN online database) revealed that CCND1 expression was significantly elevated in breast cancer cells compared with normal breast cells." (PMID 40949144, 2025). "Downstream targets CCND1 and CTGF are often highly expressed in breast cancer and linked to poor prognosis in triple-negative cases." (PMID 41614824, 2025). "Cyclin D1 protein overexpression in ERα-positive breast cancers correlates with poor responses to endocrine agents." (PMID 40565165, 2025). "Further comprehensive studies are needed in order to understand the impact of CCND1 amplifications on resulting (downstream) signaling activities and their effects in breast cancer." (PMID 39586971, 2025).
breast cancer (continued). "For instance, PI3K inhibitors decrease Cyclin D1 expression, restoring sensitivity of breast cancer cells to CDK4/6 inhibitors." (PMID 41271634, 2025). "Experimental models show that PRL stimulates MCF-7 breast cancer cell proliferation through autocrine/paracrine activation of the JAK/STAT/cyclin D1 pathway." (PMID 41370498, 2025). "IL-8 typically recruits and activates macrophages upon tissue over-injury, induces epithelial–mesenchymal transition, and, combined with an IL-6 to IL-8 ratio of 3.0, upregulates cyclin D1 to drive breast cancer cell proliferation." (PMID 40427296, 2025). "This aligns with previous studies that reported the ability of D-LMN to inhibit Cyclin D1 expression in breast cancer." (PMID 40508085, 2025). "The Tukey’s g- &-h mixtures were applied to model cellular expressions of Cyclin D1 protein in breast cancer tissues, and resulting parameter estimates evaluated as predictors of progression-free survival." (PMID 40099197, 2025). "DILA1 disrupts the phosphorylation of Cyclin D1 at Thr286 by directly binding to this site, subsequently blocking its degradation and leading to an increase in Cyclin D1 protein levels in breast cancer cells." (PMID 41348684, 2025). "This study investigated CCND1 amplification in a cohort of patients with early breast cancer, focusing on HR-positive, HER2-negative patients, and the correlation of amplification with outcome and clinicopathologic parameters." (PMID 39586971, 2025). "We used the Tukey’s g- &-h mixture model to analyze Cyclin D1 expression levels in cancer cells of treatment-naive breast cancer patients." (PMID 40099197, 2025). "Specifically, OCT1 interacts with the transactivation domain of STAT5A to promote prolactin-induced cyclin D1 expression, which encourages cell cycle progression in breast cancer." (PMID 40507264, 2025). "Studies have shown that CCND1 overexpression is found in various types of tumors, including not only lymphomas but also breast cancer, bladder cancer, parathyroid tumors, lymphomas, melanomas, lung cancer, and centrocytic lymphomas." (PMID 41305721, 2025). "Cyclin D1, a pivotal oncoprotein, is overexpressed in approximately 65% of breast cancer cases, and is essential for cancer cell proliferation and tamoxifen resistance." (PMID 41348684, 2025). "In breast cancer cells, the miR-17/20 cluster demonstrates an inverse relationship with cyclin D1 protein levels, suppressing its translation via 3′UTR binding and inhibiting cancer cell proliferation." (PMID 41230330, 2025). "From a mechanistic standpoint, CDK1 knockdown reduced AKT phosphorylation and downregulated Cyclin D1, A, and E1, leading to suppressed breast cancer cell proliferation." (PMID 41278293, 2025). "Palbociclib is currently approved for use in breast cancer and targets CCND1 through CDK4/6 inhibition." (PMID 41326661, 2025). "The CCND1 gene is amplified in ~10–20% of primary breast cancers and preferentially occurs in ERα+ tumors." (PMID 40565165, 2025). "Cyclin D1 amplification and overexpression are repeatedly found in HR-positive breast cancer and are assumed to play a central role in the development of endocrine therapy resistance." (PMID 39586971, 2025). "To date, some natural compounds have gained attention for cancer treatment, such as the inhibition of MCF7 breast cancer cells by nano-curcumin via suppression of cyclin D1 production, which affects breast cancer development and metastasis." (PMID 40296899, 2025). "Tamoxifen impacts the binding of cyclin D1 with ER and STAT3 in cyclin D1-overexpressing breast cancer cells, abolishing cyclin D1-mediated inhibition of STAT3 and growth suppression, allowing STAT3 to exhibit anti-apoptotic activity." (PMID 40949156, 2025).
breast cancer (continued). "This connection dramatically enhances transcriptional activation of ERα target genes, including Cyclin D1, c-Myc, and pS2, leading to increased proliferation of breast cancer cells and finally promoting breast cancer progression." (PMID 41179291, 2025). "CCND1 amplification is a recurring event in breast cancer, occurring most frequently in luminal B-like and HER2-amplified subtypes." (PMID 39586971, 2025). "We then applied Tukey’s g- &-h mixture to modeling distributions of cell-level Cyclin D1 protein expression in breast cancer tissues." (PMID 40099197, 2025). "Overexpression of Cyclin D1 is observed in around 50% of breast cancer cases, while the CCND1 amplification frequency is between 9–15%, and both are associated with a poor prognosis." (PMID 41348684, 2025). "Altogether, these data suggest that circFOXK2 is highly expressed and positively correlated with CCND1 in breast cancer and other cancer types." (PMID 40233410, 2025). "TB amplification elucidates the amplification mechanism of key oncogenes ERBB2 and cyclin D1 (CCND1) in breast cancer." (PMID 41030947, 2025). "For example, based on the important role of cyclin D1 overexpression in enhancing breast cancer cell proliferation, various cell cycle inhibitors targeting CDK4 have been developed to treat breast cancer." (PMID 41161384, 2025). "Up to 50% overexpression of Cyclin D1 has been noted in mammary cancer cells, some of which is due to amplification of the CCND1 gene, seen in up to 20% of breast cancers." (PMID 40940886, 2025). "The most significantly altered segments in breast cancer included 11q13.3-Amp where mitogene CCND1 is located, and 8q24.21-Amp where oncogene MYC is located." (PMID 40740860, 2025). "such as interaction of FOXO3 protein with LINC01355 stabilizes FOXO3 and in turn inhibits CCND1 transcription and hence breast cancer growth." (PMID 39912983, 2025). "Reduction of FOXO3 or overexpression of CCND1 can reverse the inhibitory action posed by LINC01355 on proliferation of breast cancer cells In TNBC another tumor suppressor lncRNA (SONE) has been investigated." (PMID 39912983, 2025). "Beta-sitosterol treatment induces G1 phase cell cycle arrest in MDA-MB-231 breast cancer cells by downregulating cyclin D1 and upregulating pro-apoptotic proteins like BAX." (PMID 40143209, 2025). "This suggests that both STAT5A and STAT5B promote cyclin D1 expression in breast cancer through interacting with different cofactors." (PMID 40507264, 2025). "In Cluster 5 (IDC), upregulated genes such as CXCL14, S100A11, CCND1, and AGR2 are linked to breast cancer progression, metastasis, and therapeutic resistance." (PMID 41182757, 2025). "Several mechanisms of tamoxifen resistance have been investigated, including the overexpression of Cyclin D1, a cell cycle regulator that promotes cell proliferation, which is overexpressed in a subset of breast cancers." (PMID 41348684, 2025). "Studies have shown that FOXM1 regulates ERα expression in breast cancer cells, and its target cyclin D1 correlates with ERα positivity." (PMID 40002266, 2025). "No further biomarker analyses have yet been published from CDK 4/6 inhibitor trials; for example, the Natalee trial (NCT03701334) examining ribociclib for adjuvant breast cancer patients will assess CCND1 as one of the biomarkers." (PMID 39586971, 2025). "Adavosertib inhibited the growth of a Palbociclib-resistant PDX model of metastatic Erα+ CCND1-driven breast cancer by 70% after 60 days of treatment in Swiss nude mice in vivo." (PMID 40565165, 2025). "This study therefore investigated the prognostic value of CCND1 amplification in hormone receptor (HR)-positive breast cancer patients." (PMID 39586971, 2025). "In breast cancer models, these conjugates induce G0/G1 phase arrest by downregulating cyclin D1/CDK4 complexes and upregulating WAF1/p21, a cyclin-dependent kinase inhibitor." (PMID 41291133, 2025).
breast cancer (continued). "Mouse experiments have demonstrated that there is a correlation between cyclin D1 overexpression and breast cancer formation." (PMID 39586971, 2025). "To investigate the clinical relevance of circFOXK2 in regulating CCND1, we first measured the expression of circFOXK2 in various breast cancer cell lines." (PMID 40233410, 2025). "PRMT5 is overexpressed in breast cancer patients, and it results in the activation of the Wnt/beta-catenin proliferative signaling pathway, leading to enhanced expression of c-myc and CYCLIN D1 and SURVIVIN." (PMID 40869229, 2025). "An increase in DILA1 expression correlates with Cyclin D1 levels enhancement and poor prognosis in breast cancer patients undergoing tamoxifen treatment." (PMID 41348684, 2025). "Specifically, cyclin D1 has been shown to be involved in driving breast cancer initiation and progression by contributing to ERα activation." (PMID 40231553, 2025). "In MCF-7 cells, a representative luminal A breast cancer cell line with low ErbB2 expression, the G1/S transition is normally regulated by the cyclin D1/CDK4 complex via Hsp90." (PMID 41161384, 2025). "SAMD4B overexpression increased Topflash luciferase activity and upregulated the expression of β-catenin, Axin2, Cyclin D1, and c-Myc in breast cancer cells." (PMID 41154652, 2025). "The rate of CCND1 amplification is 12.9% in breast cancer, most which are luminal B (51.5%) or luminal A subtype (25.8%)." (PMID 40994809, 2025). "All this occurs through the activation of the mitogen-activated protein kinase (MAPK) pathway, which is responsible for ERα transactivation and Cyclin D1 upregulation, resulting in the stimulation of breast cancer cell growth." (PMID 39996758, 2025). "Cyclin D1 becomes overexpressed following genomic rearrangement and functions as a crucial oncogene in breast cancer pathogenesis." (PMID 41230330, 2025). "Mechanistically, CDK1 knockdown reduced AKT phosphorylation and downregulated Cyclin D1, A, and E1, leading to suppressed proliferation of breast cancer cells." (PMID 41278293, 2025). "Dysregulated expression of Cyclin D1 has been connected to hormonal therapy resistance development in breast cancer treatment." (PMID 41348684, 2025). "DILA1 is a new lncRNA that interacts with Cyclin D1 and is overexpressed in tamoxifen-resistant breast cancer cells." (PMID 41348684, 2025). "Cyclin D1 overexpression is frequently found in tumors, including breast cancer, and the frequency of CCND1 amplification is between 9 and 15%." (PMID 40940829, 2025). "Deregulation of Cyclin D1 expression and/or activity is common in human cancers including bladder cancer, colon cancer, and breast cancer." (PMID 40224178, 2025). "More importantly, circFOXK2 expression is positively correlated with that of CCND1 in breast cancer cell lines and clinical breast tumor tissues." (PMID 40233410, 2025). "Overexpression of the CCND1 gene, which encodes cyclin D1 (the primary partner of CDK4/6), has been commonly observed in breast cancers resistant to CDK4/6is." (PMID 40244377, 2025). "Usage of the proximal PAS to generate shorter isoforms of CCND1 (Cyclin D1) mRNA has been associated with increased cyclin D1 protein and increased cell proliferation of HEK293T, lung cancer, and breast cancer cells." (PMID 40022203, 2025). "Genes central to the main female-biased cancers (melanoma, gastric and thyroid), breast cancer and ESR1, which encodes oestrogen receptor-α (ERα), include CDH1 (which encodes E-cadherin), CCND1 (cyclin D1), BRAF and KRAS." (PMID 40500450, 2025).
breast cancer (continued). "Cyclin D1 overexpression in breast cancer (BC) can result in constitutive activation of the CDK-cyclin pathway." (PMID 40764324, 2025). "Reduced expression of RRM2, cyclin D1, and NF-κB protein, and an elevated level of pH2AX result in decreased breast cancer growth and survival." (PMID 38473336, 2024). "In conclusion, amplification of CCND1 and overexpression of cyclin D1 are key in many breast cancers, making CDK4/6 inhibitors like abemaciclib, palbociclib, and ribociclib effective treatments." (PMID 38256428, 2024). "ERα is a major determinant of tumor growth in about 80% of breast cancers in which it controls cell cycle genes such as cyclin D1 (CCND1) and differentiation genes such as the progesterone receptor gene (PGR) and the ERα coding gene itself (ESR1)." (PMID 37989525, 2024). "We next analyzed the associations between FGF2 and FGFR1 gene expression levels and the expression of CDKN1A or CCND1 in the tumor transcriptomes of 601 ER + breast cancer patients from the Cancer Genome Atlas (TCGA)." (PMID 38553760, 2024). "A simultaneous FGFR1/CCND1 amplification and synergistic inhibition of tumor growth occur in ER+ breast cancer cells deprived of estrogen when palbociclib is combined with an FGFR inhibitor." (PMID 38275906, 2024). "CDK4 is an enzyme that works with cyclin D1 to promote cell cycle progression by activating Rb, and overexpression of CDK4 has been linked to certain types of breast cancer, as well as other cancers." (PMID 38332687, 2024). "ER− MDA-MB-468 breast cancer cells exhibited an approximately 19-fold higher expression of CCND1 and 4-fold greater expression of RRM2 as compared to MCF7 cells." (PMID 38473336, 2024). "Ultimately, our data suggest a strategy to target RRM2, NF-κB and cyclin D1 to supplement traditional therapies as well as offering improved efficacy for breast cancer treatment." (PMID 38473336, 2024). "Previous studies have revealed the regulatory role of RBMS3 in deactivating the Wnt/β‐catenin signaling pathway and repressing the expressions of diverse genes, including β‐catenin, cyclin D1, and C‐myc, within breast cancer cells." (PMID 38618967, 2024). "RBMS3 also significantly inhibited the expression of β-catenin, cyclin D1 and c-Myc proteins in breast cancer cells." (PMID 38783078, 2024). "Previously, natural remedies from pericarp extract of Baneh enhance G1 phase cell cycle arrest and downregulate the expression CDK and cyclin D1, thereby inhibiting human breast cancer." (PMID 39574470, 2024). "Clinical studies in bioinformatics have indicated a positive correlation between ESR1 and either CCND1 or BCL2 gene expression in all breast cancer patients." (PMID 39202273, 2024). "We observed that DDX inhibited cyclin D1 expression alone or in combination with palbociclib in parental and palbociclib-resistant ER+ and ER− breast cancer cells." (PMID 38473336, 2024). "Intensive studies have been conducted to establish cyclin D1 as a prognostic biomarker in breast cancer." (PMID 38473336, 2024). "We also found evidence that RRM2 and cyclin D1 levels are upregulated in ER− palbociclib-resistant breast cancer, giving rise to a difficult-to-treat breast cancer population." (PMID 38473336, 2024). "Among them, 18 genes were essential for cancer cell proliferation, such as NSF for breast cancer, CCND1 for renal cell cancer, DHX16 for lung cancer, CDC27 for ovarian cancer, and CTDP1 for prostate cancer." (PMID 39025880, 2024). "LINC01355 interacts with FOXO3a protein and prolongs the half-life of FOXO3a protein, leading to transcriptional repression of Cyclin D1 to induce breast cancer cell cycle arrest." (PMID 38505423, 2024). "Inhibition of c-Myc or cyclin D1 activity eliminates oestrogen-stimulated proliferation of breast cancer cells, while induction of c-Myc or cyclin D1 can mimic the effects of oestrogens." (PMID 39125736, 2024).